IGF1 (insulin like growth factor 1)
Diseases named in the same sentence as IGF1 in open-access papers (continued):
Sharing a sentence is not in itself a finding about the gene and the disease.
tumor (continued). "There are various cellular sources of IGF-1 in the tumor stroma, and the reduction in stroma-derived IGF-1 that we observed may explain the growth inhibition of PDAC cells in vivo when Hh signaling was blocked." (PMID 20098680, 2010). "In addition to its effects on 4T1.2 tumour cells, IGF1 stimulated growth of human dermal MVECs, an effect that was blocked by recombinant IGFBP4." (PMID 19536088, 2009). "We hypothesised that a protease-resistant IGFBP4, however, would inhibit 4T1.2 tumour growth by binding IGF1 rendering it biologically inactive even in the presence of PAPP-A." (PMID 19536088, 2009). "Subsequent maintenance of tumor growth may require tumor cell-autonomous IGF-1 production and IGF1 induction may provide one mechanism whereby EWS-FLI-1 and its ESFT-associated relatives ensure tumor growth and progression." (PMID 18648544, 2008). "Interestingly, in subgroup 6, the 6 normal breast tissues (called CP) clustered together with a group of tumours that overexpressed IGF1, a feature which is characteristic of normal-like tumours." (PMID 17338809, 2007). "We previously used linear regression analysis to show that blood glucose levels could predict CT-2A growth as well as insulin-like growth factor 1 (IGF-1) levels, which influences tumor angiogenesis." (PMID 17313687, 2007). "Also, restriction of either diet significantly reduced the plasma levels of IGF-1, a biomarker for angiogenesis and tumour progression." (PMID 14520474, 2003). "Thus, losartan exerts multicompartmental effects, simultaneously acting on the vasculature (improved perfusion), immune compartment (enhanced immune infiltration and activation), and tumor cells (attenuated IGF-1 signaling), while indirectly reshaping CSC-supportive niches through ECM normalization." (PMID 41596584, 2026). "In parallel, losartan shifts the immune landscape towards an immunostimulatory state, increasing CD8+ T cells, NK cells, and activated dendritic cells, while limiting Tregs and MDSCs, and may further sensitize tumor cells by suppressing IGF-1-mediated survival pathways." (PMID 41596584, 2026). "Furthermore, understanding the distinct roles of IGF1 isoforms in tumour biology may provide insight into optimising IGF1-targeted therapies overcoming resistance mechanisms." (PMID 39796756, 2025). "HuR is involved in tumor-associated lymphangiogenesis through post-transcriptional mechanisms, potentially mediating lymphangiogenesis in the TME by influencing the expression of growth factor ligands and receptors, such as insulin-like growth factors 1 and 2 (IGF-1 and IGF-2)." (PMID 41200195, 2025). "Low GH levels have been correlated with a reduced incidence of neoplasia, though it is still controversial whether GH plays a direct role in promoting per se the occurrence of neoplasia; the possible correlation could also relates to other co-factors, such as IGF-1." (PMID 40088375, 2025). "The heterogeneity of EC, including variations in IGF1 expression across tumour subtypes, further complicates the development of effective therapies and underscores the need for predictive biomarkers to identify patients most likely to benefit from IGF1-targeted treatments." (PMID 39796756, 2025). "In addition, the SeC secretome is characterized by the presence of trophic factors, including insulin-like growth factor-1, whose signaling could potentially contribute to tumor cell motility and promote cell invasion and metastasis." (PMID 38534388, 2024). "Similarly, after the application of SSA, cases 1, 6, 7, 8, and 10 also showed a mild decrease in thyroid hormone levels, and after undergoing TSS to remove the tumor, there was a significant decrease in GH/IGF-1 levels, accompanied by a further significant decrease in thyroid hormone levels." (PMID 38349236, 2024). "In addition, tumor cells expressed much lower levels of IGF-1 than osteoclasts." (PMID 38342894, 2024).
tumor (continued). "Also, IGF1 and tumor diameterand volume at treatment initiation time were higher in the noncontrolled patients:IGF1-SDS 10.4 (8.0-12.2) vs 5.2 (4.1-6.8) SDS, P < .001; diameter 23 ±9 vs 15 ± 7 mm, P = .02; and volume 3478 (2983-6511) vs 947 (187-2088)mm3, P < .01." (PMID 38943661, 2024). "Thus, the study supported the concept that PAPP-A may increase tumor growth via its ability to promote IGF-1 action in the local tumor milieu." (PMID 38396692, 2024). "Thus far, it is unclear whether this regulation is divergent during ADT and related tumor progression, which may lead to aberrant activation of IGF1 to promote tumor progression and hormone refractoriness, resulting in CRPC development." (PMID 39369165, 2024). "Since osteoclasts were reported to secrete IGF-1 in the skeletal microenvironment, and GM-CSF has been reported to induce IGF-1 expression, and tumor cells usually produce GM-CSF abundantly, we explored whether IGF-1 expression of osteoclast is regulated by GM-CSF." (PMID 38342894, 2024). "Because aberrant IGF1 and Wnt activation has been shown to directly induce prostate oncogenesis and PCa development, these findings implicate stromal AR in Gli1-lineage cells acting as tumor niches to support prostate epithelial oncogenesis through IGF1/Wnt activation." (PMID 39369165, 2024). "The dual repression of IGF1 signaling evoked by CR is significant as a reduction in ligand alone is difficult to achieve in humans and may not always lead to meaningful pathway suppression and downstream inhibition of tumor growth and progression." (PMID 37686596, 2023). "Therefore, some compounds secreted by tumor cells or the low IGF1 level measured could have downregulated the Akt/mTOR pathway, leading to a decrease in protein synthesis." (PMID 36980729, 2023). "A number of growth factors, including IGF-1, FGF, and HGF, have also been found to associate with the ECM, and alterations in composition of the ECM due to obesity may alter the reservoir of growth factors stored in the ECM during tumor progression." (PMID 35435599, 2022). "Next, we wanted to investigate whether IGF1 influences glucose uptake into the tumor cells." (PMID 35574343, 2022). "Besides the tumor immune escape pathway, genetic markers belonging to cytokines/interleukins (IL-8 and its receptors) and angiogenic mediators (IGF1) seem to be the best investigated and hopefully most promising to be translated into clinical practice after validation." (PMID 36432658, 2022). "Additionally, IGF-1 secretion promotes tumor cell proliferation and tumor growth." (PMID 36357661, 2022). "Importantly, in our in vivo models, we have shown that N157 treatment reduces UM tumor growth, indicating that targeting IGF-1/IGF-1R signaling could be a potential therapeutic strategy." (PMID 36551732, 2022). "However, the correlation with GH and tumor volume was stronger for sKl than for IGF-1." (PMID 36042253, 2022). "Moreover, the study detected few associations between IGF-1 and Ki-67, IGF-2, and tumor stage." (PMID 34638601, 2021). "Besides, animal model suggests that the overexpression of C-erbB-2 and activation of IGF-1 signaling pathway can promote rapid growth and metastasis of tumor cells, while low expression of C-erbB-2 and inhibited activation of IGF-1 signaling pathway can inhibit the growth and metastasis of EC cells." (PMID 34233689, 2021).
tumor (continued). "Additionally, tumor cells' characteristics such as receptors (insulin/IGF1) and pathway proteins (PI3K/mTOR, LKB1, and TSC2) expression might potentially mediate these indirect, host-mediated effects and any direct effects that are extremely important." (PMID 33531904, 2021). "Moreover, miR-186-3p expression was negatively correlated with IGF1 expression in tumor tissues." (PMID 34253194, 2021). "Furthermore, IGFs have been shown to increase survival and proliferation in NB cells, PC cells, and MM cells in vitro, suggesting that IGF-1 released from the bone matrix in the proximity of metastatic tumor cells could also directly benefit tumor progression." (PMID 33287630, 2021). "AVE1642 treatment by targeting IGF-1 could increase the paclitaxel-mediated anti-tumor effect." (PMID 33768092, 2021). "Both insulin and IGF-1 could act as growth factors for tumor cells." (PMID 33727597, 2021). "While silenced C-erbB-2 expression and inactivated IGF-1 signaling pathway caused decreased mRNA and protein expressions of IGF-1, IGF-1R and Akt, decreased cell proliferation, migration and invasion, prolonged G0/G1 phase and shortened S phase, increased cell apoptosis, and inhibited tumor growth." (PMID 34233689, 2021). "In this study, we examined the IGF1 expression level in clinical PTC tissue specimens and found that the expression of IGF1 in PTC tissue samples was higher than that in adjacent normal specimens and was significantly associated with tumor size, TNM staging, and Lymph node metastasis." (PMID 32851683, 2020). "This association may be because a high insulin concentration increases the concentration of insulin-like growth factor 1, which, in turn, can upregulate vascular endothelial growth factor secretion and induce tumor angiogenesis, leading to tumorigenesis and metastasis." (PMID 32313131, 2020). "It has been hypothesized that metformin could act with both direct and indirect mechanisms, primarily decreasing glucose, IGF-1 and insulin signaling, thereby creating an unfavorable environment for tumor growth that is similar to that created by caloric restriction." (PMID 30635619, 2019). "Activity in patients with predominant bone metastases may reflect preclinical evidence that tumor cells are primed to metastasize to bone by high IGF-1 secreted by stromal components of the primary tumor, suggesting that bone metastases may reflect IGF dependency." (PMID 31416218, 2019). "However, the exact mechanism of this phenomenon remains unclear, and revealing it will require the measurement of IGF-1 and GH levels to monitor tumor activity." (PMID 30916168, 2019). "Resistance to SSAs may be defined as a failure to achieve biochemical control criteria (GH< 1.0 μg/L and a normal age-adjusted IGF-1) and increase in tumor size or tumor shrinkage <20% compared with baseline volume after at least 12 months of treatment with SSAs." (PMID 31191457, 2019). "Concomitantly, cells treated with both nobiletin and IGF1 showed higher tumor viability than cells treated with nobiletin alone, implying that activating AKT could reverse the antitumor effects of nobiletin, and confirmed that nobiletin could indeed inhibit tumor growth via the AKT pathway." (PMID 31354472, 2019). "Thus, the existence of a crosstalk between p63 and the IGF1 system may represent a mechanism by which tumours that overexpress ΔNp63 escape apoptosis and acquire a proliferative advantage." (PMID 30594912, 2018). "Thus, despite the positive association between cytoplasmic IGF-1 expression and the parameters of tumour size and distant metastasis in ILC patients, this did not impact upon survival outcomes." (PMID 30337563, 2018). "This hypothesis, however, does not exclude a possibility that GHRH agonists may also bind to an unknown homologous G-protein coupled receptor and directly inhibit the IGF-1 production in both hepatic and tumor cells as proposed by Kineman for the actions of GHRH antagonists." (PMID 29983893, 2018).
tumor (continued). "Therefore, we conclude that IGF-1 may be an important candidate that IL-15 facilitates tumor growth." (PMID 29255466, 2017). "We further assessed whether CD215+ myeloid cells contribute to tumor progression via IGF-1 in vivo." (PMID 29255466, 2017). "We hypothesize that the decreased tumor latency time by X10 and IGF1 treatment was caused by enhancing the tumor development rather than interfering with the tumor initiation." (PMID 28173837, 2017). "However, our results shed light on the possibility that IGF-1 may be an important candidate that IL-15 facilitates tumor growth." (PMID 29255466, 2017). "The most frequently proposed hypotheses are the indirect effects of reducing levels of insulin and even insulin-like growth factor 1 (IGF-1), which is closely related to insulin signaling and exerts direct effects on the activation of cellular pathways of tumor cells." (PMID 28409158, 2017). "However, expression of IGF-1 appears to be inconsistent across different types of tumours." (PMID 28143425, 2017). "In addition high levels of IGF1 promote several forms of neoplasia that would shorten life." (PMID 28490690, 2017). "NDUFA4L2 may interact with 14 tumor-related proteins, participate in growth and death processes and be involved in ccRCC-related pathways, such as insulin-like growth factor 1 (IGF-1), mammalian target of Rapamycin (mTOR) and phosphoinositide 3 kinase serine/threonine protein kinase (PI3K/AKT)." (PMID 29158991, 2017). "Moreover, the targeting of IGF-1 might also interfere with the immunomodulatory properties of tumor cells." (PMID 27764776, 2016). "Theoretically, high energy intake can play a relevant role in several neoplasms since it may stimulate the sympathetic nervous system and basal metabolism leading to increased IGF-1 release which increases cell proliferation automatically through the stimulation of mitosis." (PMID 27975054, 2016). "IGF-1, as happens with other hormone therapies (thyroid hormone or insulin), should never been used lightly without firstly assessing its deficiency (local, central or systemic) and secondly by ascertaining that no tumours are near to be generated." (PMID 26733412, 2016). "Also, IGF-1 has a potential of promoting neoplasm metastasis." (PMID 27835910, 2016). "Therefore, the reduction in plasma IGF1 and insulin by MR suggest that the reduced levels in the insulin/IGF1 axis may inhibit tumor development in this xenograft model." (PMID 27255182, 2016). "The observed association with chocolate could be biologically plausible, because the high amount of carbohydrates in chocolate could stimulate IGF-1 production as a possible mechanism contributing to increased tumor growth and a more malignant behavior of the disease." (PMID 27400803, 2016). "Moreover, exercise may have a potential beneficial effect on tumor outcome by reducing insulin resistance and insulin/insulin-like growth factor-1 (IGF-1) secretion." (PMID 26458923, 2015). "Indeed, ghrelin may increase the levels of growth factors, such as GH and IGF-1 that stimulate tumour growth." (PMID 26523094, 2015). "Furthermore, the effect of caloric restriction in IGF-1 levels may regulate luminal tumor growth by modulating the epithelial-mesenchymal transition (EMT) process and chemokine milieu." (PMID 25743390, 2015). "This reduction in the tumor growth by 2-DG could be, in part, due to reduced insulin levels leading to attenuation of the insulin/IGF-1/PI3K/Akt/HIF-1α signaling pathway thereby possibly modulating the various cell cycle regulatory proteins (cyclin D, A, E) involved in the proliferation." (PMID 26135741, 2015). "However, this tumour could have already been subclinically present at the beginning of the IGF-1 treatment, because his baseline level of IGF-1 was 3.279 ng/ml (N = <2.5)." (PMID 26331034, 2014). "Thus, we may hypothesize that IGF1 secreted by HCC cells serves to downregulate miR-122 in the surrounding normal cells and causes tumour progression." (PMID 24813441, 2014).
tumor (continued). "Down-regulation of the somatotropic axis, including a reduction in insulin-like growth factor-1 (IGF-1), likely plays an important role in CR-induced lifespan extension, possibly by reducing cell proliferation rates, thereby delaying replicative senescence and inhibiting tumor promotion." (PMID 25369265, 2014). "Thus, in the present case it seems, the proliferation of tumour cells might be rather supported by increased effect of IGF1, IGF2 and IGF1R homodimer associations, than IGF1, IGF2 and INSR-IGF1R heterodimer associations or INSR effects on IRS1." (PMID 25496518, 2014). "Normalization of IGF-1 levels represents the main end point of Pegvisomant treatment (HQ) although sudden and remarkable GH increase during Pegvisomant therapy could be a marker of tumor re-growth (VLQ)." (PMID 25245336, 2014). "Therefore, PAPPA might serve as a better therapeutic target for MPM with more tumor specificity and less risks of side effects as compared to IGF-1 axis components as targets." (PMID 23896451, 2013). "Indeed, the serum insulin- and IGF-1-lowering effects of metformin have been thought to explain why the administration of metformin suppresses tumor development or growth in multiple experimental models, including colon, hematopoietic, and mammary cancer models." (PMID 23986086, 2013). "Moreover, results suggest that IGF1 may play an important role even at the early stages of tumor formation." (PMID 24282616, 2013). "Thus, such a tumor environment where IGF-1 may directly and indirectly stimulate tumor expansion seems optimal for validating the therapeutic potential of developed antagonists to the IGF-1R signal in MM." (PMID 22348393, 2012). "Notably, the shift of IGF-1, another IGF1-R ligand, also indicated association with the tumor state, yet the IGF1 gene was potentially downregulated in tumor cells (data not shown)." (PMID 21464922, 2011). "Thus, it may depend on the circumstances which variables - including blood glucose, insulin, lactate, IGF1, fat quality and ketone bodies - are the best predictors of and responsible for the anti-tumor effects of very low CHO diets." (PMID 22029671, 2011). "Therefore, IL-4 was added to wells containing primary naïve and tumor-educated BAL macrophages to determine if alternative activation could increase IGF-1 production in either macrophage group." (PMID 21699731, 2011). "Our study only examined mice into adulthood, and while we observed no obvious pathologic consequences in these animals, longer-term studies may be needed to address the possibility that high IGF-1 levels during growth affect tumor development or other pathology later in life." (PMID 20200935, 2010). "Thus, IGF-1 is an important target of Hh signaling in BM-derived cells, and the downregulation of IGF-1 in tumor xenografts by cyclopamine treatment could contribute to the disruption of angiogenesis." (PMID 20098680, 2010). "Therefore, IRS-2 may promote tumor progression by stimulating a positive feedback loop to enhance IGF-1 signaling." (PMID 19534786, 2009). "The IGF1 inhibitor, on the other hand, may be best used concurrently with chemotherapy as a sensitizer in metastatic or neoadjuvant settings, in which contexts tumor shrinkage may be a sensitive measure of its value." (PMID 20011464, 2009). "As IGF1 increased VEGF production by the 4T1.2 cells and stimulated MVEC proliferation, we anticipated that an antiangiogenic effect might underlie this inhibition of tumour growth." (PMID 19536088, 2009). "Wild-type IGFBP4 may paradoxically increase tumour growth by serving as a reservoir of IGF1." (PMID 19536088, 2009). "IF has been shown to modulate this signaling pathway by decreasing circulating IGF-1 levels, leading to downregulation of the PI3K/AKT/mTOR pathway, a central driver of tumor growth." (PMID 41008741, 2025). "Our data, showing elevated IGF1 in NPC patients with metastasis and poor prognosis, align with studies suggesting that IGF1 can enhance tumor invasiveness." (PMID 41333209, 2025).